IL17A (interleukin 17A)
Diseases named in the same sentence as IL17A in open-access papers (continued):
Sharing a sentence is not in itself a finding about the gene and the disease.
psoriasis (continued). "In addition, IL-17A plays an important role in cutaneous defense by the cooperation with other psoriasis-associated cytokines such as IL-22, TNF-α and IL-1 which have been implicated in a synergistic induction of AMP in keratinocytes." (PMID 23555696, 2013). "IL-17A has been implicated as an important cytokine in the pathogenesis of psoriasis." (PMID 23468834, 2013). "On the other hand, IL-17A has been implicated in the pathogenesis of many chronic inflammatory disorders and clinical trials with IL-17A-neutralizing antibodies have reported benefit in patients with psoriasis and rheumatoid arthritis." (PMID 23109839, 2012). "Moreover, mice with keratinocyte‐specific Fads2 knockdown exhibited increased mRNA levels of psoriasis‐associated inflammatory mediators, including Il17a, Il1b, and Cxcl1, in both the dorsal and ear skin, and greater neutrophil infiltration was confirmed by flow cytometry." (PMID 40878384, 2025). "Interestingly, in HLA-Cw6+ patients experiencing guttate psoriasis flare-ups associated with pharyngitis, the Th17-associated response is more pronounced, leading to significantly elevated levels of IL-17A, IL-17F, and IL-6, which are involved in Th17 differentiation." (PMID 40303401, 2025). "Thus, the inhibition of IL-17A may represent a potential therapeutic strategy for psoriasis and psoriasis-associated dyslipidemia by alleviating autophagy inhibition." (PMID 38606161, 2024). "Therefore, we explored whether Psoriasis is associated with alterations in selected gut/skin microbiota in a study cohort, and a longitudinal cohort study to reveal the effects of IL-17A inhibitor treatment on gut microbiota in Psoriasis." (PMID 38482003, 2024). "Experimental animal models of chronic inflammatory conditions such as posterior uveitis, psoriasis, inflammatory bowel disease, multiple sclerosis, collagen-induced arthritis, and ankylosing spondylitis have highlighted the significant pathogenic impact of IL-17A." (PMID 38672170, 2024). "Thus, our data imply that inhibition of IL-36 signaling constitutes an attractive, alternative approach for the treatment of IL-17A-driven plaque psoriasis, which may also effectively inhibit psoriasis-associated comorbidities." (PMID 38162658, 2023). "In addition, cytotoxic CD8+ T (Tc) cells can also express IL-17A (Tc17) upon recognition of the self-antigen ADAMTSL5 via HLA-C*06:02 which is the strongest psoriasis susceptibility allele in psoriasis patients revealing their pivotal pathogenic role in psoriasis." (PMID 37594540, 2023). "IL-17A, the best known of these cytokines, has been linked to the pathogenesis of autoimmune and chronic inflammatory diseases, and its blockade with monoclonal antibodies has proved efficacious in psoriasis (PsO), psoriatic arthritis (PsA), and axial spondyloarthritis (axSpA)." (PMID 37373452, 2023). "In addition, pretreatment of HaCaT cells with polar microalgae extracts significantly decreased expression of IL1B, IL23, CXCL1, and IL17A mRNA, which are mediators implicated in the pathogenesis of psoriasis, compared to HaCaT cells treated with only M5 cytokines." (PMID 37438821, 2023). "This article reviews the recent literature on PRs associated with TNF-α, interleukin (IL)-12/23 (p40), IL-17A/the IL-17 receptor (R), IL-23 (p19), and IL-4Rα inhibitors, which are commonly used for dermatological conditions, especially atopic dermatitis (AD) and psoriasis." (PMID 35884790, 2022). "In particular, the NFkB-activating cytokines (LTA, IL-1B) are expected to synergize with IL-17A and IL-17F for the induction of many typical “IL-17 pathway” products in keratinocytes that initiate “feed forward” inflammation and help to maintain pathogenic gene expression profiles in psoriasis." (PMID 36110854, 2022). "Thus, TNF-α/IL-17A/IFN-γ induced a psoriasis condition, ultimately causing skin hyperkeratosis." (PMID 36015080, 2022). "In addition, IL-17A signaling is an important pathogenic mechanism of psoriasis." (PMID 35372072, 2022).
psoriasis (continued). "IL-17A, which is involved in the development of psoriasis, is also implicated in the pathogenesis of CVDs, which suggests that IL-17A-mediated inflammation may become a potential overlapping pathological mechanism between psoriasis and its cardiovascular comorbidities." (PMID 34803716, 2021). "Although a series of different overlapping mechanisms have been found to establish a link between psoriasis and cardiovascular diseases, the underlying mechanisms of the two types of diseases and the potential efficacy of IL-17A mAbs in amelioration of cardiovascular comorbidities remain unclear." (PMID 33602246, 2021). "In a mouse model of imiquimod-induced psoriasis, resveratrol administration significantly diminished the severity of skin lesions and was associated with beneficial modifications in expression of retinoic acid stimulated genes, and IL-17A and IL-19 mRNA levels." (PMID 33499118, 2021). "We speculate the increased IL-17A in the gastrointestinal tract may be the cause of the less reduction of IL-17A in the skin lesion, which in susceptible individuals may trigger the development of psoriasis states." (PMID 34881280, 2021). "Finally, it has been recently suggested that IL-17A may play a role in depression associated with psoriasis and obesity." (PMID 34829952, 2021). "Because of the link between IL-17A and neutrophil infiltration in atherosclerotic plaques and its key role in the pathogenesis of psoriasis it has been suggested that the IL-17A/neutrophil axis could take part to atherogenesis associated with psoriatic disease." (PMID 29971067, 2018). "Additionally, IL-17A is considered to be pathogenic in several autoimmune diseases and IL-17A blocking antibodies are currently used for treating autoimmune diseases like rheumatoid arthritis and psoriasis." (PMID 30061888, 2018). "Aberrant activation of Th17 cells and their effector cytokines IL-17A and GM-CSF are implicated in the pathogenesis of various autoimmune and inflammatory diseases such as systemic lupus erythematosus, rheumatoid arthritis, psoriasis, dermatomyositis, allergy, asthma, and others." (PMID 28352269, 2017). "The TH17-derived IL-17A cytokine is a potent inflammatory cytokine that has been implicated in a growing list of autoimmune diseases, for example, multiple sclerosis, Crohn's disease, rheumatoid arthritis, psoriasis, systemic lupus erythematosus, and SS, as well as autoimmunity in animal models." (PMID 21182786, 2010). "By specifically binding to interleukin-17A, ixekizumab inhibits its activity, thereby modulating the immune response and alleviating the clinical manifestations of psoriasis." (PMID 41496107, 2026). "In psoriasis skin lesions, the level of IL-17C is approximately two orders of magnitude greater than that of IL-17A." (PMID 40536951, 2026). "Immunological and genetic studies have identified the cytokine interleukin (IL)-17A as a key driver of psoriasis pathogenesis." (PMID 41575986, 2026). "From a mechanistic perspective, our results further support the biological rationale for dual IL-17A and IL-17F blockade in refractory psoriasis." (PMID 41590520, 2026). "Supporting the concept that hematologic indices reflect inflammatory burden, baseline low MLR (monocyte‐to‐lymphocyte ratio, a hematologic index correlating with SII) forecasts 52‐week PASI100 response to IL‐17A/F blockade in psoriasis." (PMID 41583119, 2026). "An external validation cohort included 511 psoriasis patients receiving IL-17A inhibitor across 26 hospitals in China." (PMID 41958571, 2026). "In-depth psoriasis pathology research now recognizes IL-17A as a central effector in disease pathogenesis." (PMID 40536951, 2026). "IL-17A, often elevated in inflammatory skin diseases such as psoriasis, signals through IL-17R to induce fibroblast production of chemokines and antimicrobial peptides." (PMID 41598494, 2026).
psoriasis (continued). "This case highlights a recalcitrant presentation of psoriasis that responded for the first time to IL-17A/F inhibition with bimekizumab." (PMID 41446699, 2026). "Further support for this link comes from the findings that neutralizing antibodies directed against IL-17A, IL-17RA and IL-23 are efficacious in diseases like psoriasis, psoriatic arthritis and ankylosing spondylitis." (PMID 39820614, 2025). "IL-17A is involved in dermatitis, arthritis, gastrointestinal inflammation, the central nervous system, and cardiovascular inflammation in psoriasis; however, data on its involvement in conjunctival diseases remain limited." (PMID 40861543, 2025). "Using a cytokine cocktail containing IL-17A, interferon-gamma and tumour necrosis factor-alpha to produce a psoriasis-like phenotype, a role for ALOX15B in human epidermal keratinocyte inflammation was investigated." (PMID 39843435, 2025). "During IMQ-induced psoriasis, there were more IL-17A–producing epidermal γδ T cells than controls, but this increase was just short of reaching significance (P = 0.075)." (PMID 40073267, 2025). "Bimekizumab, a dual inhibitor of IL-17A and IL-17F, is currently undergoing clinical trials for indications such as psoriasis, PsA, and ankylosing spondylitis." (PMID 40141149, 2025). "Bimekizumab, a humanized monoclonal IgG1 antibody that neutralizes both IL-17A and IL-17F, has shown substantial efficacy in the treatment of psoriasis (PSO), psoriatic arthritis (PsA), and AxSpA." (PMID 40076933, 2025). "Molecular profiling demonstrates concurrent upregulation of IL-17A and IL-12/23p40 in cutaneous, lymphatic, and splenic tissues, paralleling findings in psoriasis patients with A20 haploinsufficiency." (PMID 41583484, 2025). "Secukinumab is a monoclonal antibody that selectively neutralizes interleukin-17A and has shown efficacy in the treatment of psoriatic arthritis, psoriasis, and axial spondyloarthritis." (PMID 40084348, 2025). "Immunologically, psoriasis is driven by the activation of Th17 and Th1 cells, which secrete cytokines such as IL-17A, IL-22, and TNF-α." (PMID 40558675, 2025). "The IL-23-IL-17A axis is pivotal in the pathogenesis of psoriasis, as evidenced by the success of biologic agents targeting IL-23 and IL-17A in psoriasis treatment." (PMID 40161116, 2025). "An example is bimekizumab, which inhibits IL-17A and IL-17F, leading to superior efficacy over IL-17A blockade alone in psoriasis and spondyloarthropathies." (PMID 41041324, 2025). "Psoriasis and hidradenitis suppurativa are chronic inflammatory skin diseases with common pathogenesis, such as the involvement of IL-17A, which also plays an essential role in the development and metastasis of colorectal cancer." (PMID 41142781, 2025). "Some studies investigated the presence of several disease-specific inflammatory cytokines such as TNF, IL-1β, IL-17A, IL-23, and other cytokines in patients with psoriasis, which were elevated compared to controls." (PMID 39775226, 2025). "In this report, we present a case of MTC in a patient with psoriasis treated with secukinumab (Cosentyx), a monoclonal antibody targeting interleukin-17A." (PMID 41179072, 2025). "The complementary roles of TNF-α and IL-17A in driving inflammation make them critical therapeutic targets and biomarkers in psoriasis research." (PMID 40892753, 2025). "A targeted anti-IL-17A approach using Ixekizumab has shown promise in reducing depressive symptoms in 40% of psoriasis patients with co-occurring MDD." (PMID 40649841, 2025). "Secukinumab and ixekizumab (anti-IL-17A antibodies), as well as bimekizumab (anti-IL-17A/F antibody), are effective drugs used in the biological therapy of psoriasis." (PMID 41002407, 2025). "Generally, the IL-17 family consists of six members (IL17A–F), among which IL-17A displays a strong correlation with the pathogenesis of psoriasis." (PMID 40920623, 2025).
psoriasis (continued). "In psoriasis, several anti-IL-17 monoclonal antibodies are currently used in treatment, targeting IL-17A or the IL-17RA receptor and blocking the inflammatory pathway involved in the pathogenesis of this disease." (PMID 40895550, 2025). "A pivotal cytokine IL-17A has gained traction as a therapeutic strategy in pathogenesis of autoimmune and inflammatory conditions such as psoriasis." (PMID 40892753, 2025). "Th1 and Th17 cells play a key pathogenic role in psoriasis through the release of several cytokines including tumor necrosis factor alpha (TNF-α), and IL-17A, which, in turn, trigger the release of IL-6 and IL-1α by keratinocytes." (PMID 40046180, 2025). "At present, biological agents such as tumor necrosis factor alpha (TNF-α) and interleukin-17 (IL-17A) inhibitors are widely used to treat psoriasis and have achieved good clinical efficacy." (PMID 40441209, 2025). "Dendritic cells and macrophages in the dermis of psoriasis produce IL-23, which induces the activation of Th17 cells and γδ T cells and the release of inflammatory cytokines, such as IL-17A, IL-17F, IL-22, IL-6 and tumor necrosis factor-α (TNF-α)." (PMID 40303403, 2025). "Psoriasis is driven by the IL-23–IL-17 axis with IL-17A and IL-17F promoting keratinocyte activation, neutrophil recruitment and sustained cutaneous inflammation." (PMID 41303386, 2025). "Erythrodermic psoriasis shares the TNF/IL-17A inflammatory axis with plaque psoriasis, but there is a unique immunophenotype of Th2/Th17 coactivation in erythrodermic psoriasis." (PMID 40303401, 2025). "Several interleukins including IL-17A, IL-22, IL-23, IL-36γ, IL-6, and IL-1β have emerged as the potential biomarkers of subclinical inflammation and treatment resistance in psoriasis." (PMID 40731810, 2025). "In psoriasis, clinical studies with neutralizing antibodies towards IL-17A and IL-23 have demonstrated efficacy." (PMID 39820614, 2025). "Ixekizumab, a monoclonal antibody targeting IL-17A, is approved for psoriasis (PsO) and psoriatic arthritis (PsA)." (PMID 40408459, 2025). "Psoriasis is an immune-mediated inflammatory disease driven by abnormal IL-17A–IL-23 axis activation." (PMID 40360755, 2025). "In summary, ACC1 deficiency restrains IL-17A-producing γδT17 cells in the skin and skin-draining LNs of mice with IMQ-induced psoriasis." (PMID 40360755, 2025). "Psoriasis, a Th17/IL-23-mediated skin disorder, has also been found to occur more frequently in ASD, potentially linked to elevated IL-17A expression observed in both skin and brain tissues." (PMID 41277234, 2025). "The findings of our study suggest that the anti‐inflammatory properties of anti‐IL17A (M2) aptamer are amplified when conjugated with AuNPs in the psoriasis‐like model." (PMID 41477217, 2025). "Upon CD8 T cell activation, IL-17A and IL-17F were expressed at low and comparable levels in psoriasis patients and healthy controls." (PMID 40391222, 2025). "The rationale for investigating these biomarkers stems from studies demonstrating that serum levels of TNF-α, IL-17A, IL-17F, and IL-12/23 play a critical role in the development of psoriasis clinical manifestations and response to treatment." (PMID 40699767, 2025). "Bimekizumab, a monoclonal antibody that targets IL-17A and IL-17F, received marketing approval in Europe in 2021 and in Japan in 2022 for the treatment of psoriasis and PsA." (PMID 40303401, 2025). "Recent evidence indicates that various cells, such as mast cells, γδ T cells, αβ T cells, and innate lymphoid cells found in psoriasis skin lesions and synovial fluid, can also produce IL-17A." (PMID 40303401, 2025). "Antibodies such as secukinumab, ixekizumab, and brodalumab have been designed to inhibit IL-17A signaling and are currently used in the treatment of psoriasis." (PMID 40892753, 2025). "One of the most important cells in the development of psoriasis is Th17, which produces IL17A and stimulates keratinocytes, endothelial cells, and immune cells." (PMID 41477217, 2025).
psoriasis (continued). "Treatment with TP demonstrated efficacy in alleviating IMQ-induced psoriasis-like skin lesions in mice and inhibiting HaCaT cell hyperproliferation induced by IL-17A." (PMID 40365308, 2025). "Individuals with psoriasis exhibit increased levels of IL-1, IL-17A, and IL-36, compared to those with healthy skin." (PMID 40572779, 2025). "A recent study demonstrated that HMGB1 can promote Th17 cell differentiation from PBMCs derived from psoriasis patients and can increase the production of its effective cytokine IL‐17A in a dose-dependent manner." (PMID 40308590, 2025). "For instance, the immune checkpoint protein programmed death protein-1 (PD-1) was found to be expressed by cutaneous IL-17A-producing T cells in psoriasis patients and in psoriasis-like mouse models." (PMID 40391222, 2025). "Next, to better simulate the inflammatory cascade characteristic of psoriasis, we stimulated KCs with a combination of IL‐22, IL‐17A and TNF‐α, known to synergistically enhance the proinflammatory effects of IL‐22 in KCs." (PMID 40038877, 2025). "Psoriasis is a chronic, relapsing autoimmune skin disease induced by IL-17A.411–413 The existence of TRM cells usually aggravates psoriasis." (PMID 39820040, 2025). "Building on this approach, IL-17A blockers (secukinumab, ixekizumab) and IL-23 inhibitors (guselkumab, risankizumab) have shown remarkable success in psoriasis, psoriatic arthritis, and ankylosing spondylitis." (PMID 41041324, 2025). "According to previous clinical data analysis, macrophage markers and inflammatory cytokines such as TNF-α, IL-1β, IL-17A, and IL-23A are highly expressed in skin samples from psoriasis patients." (PMID 40362523, 2025). "The success of therapies targeting the IL-17 pathway, which inhibit IL-17A and its receptor, further underscores the critical contribution of RORγt-driven Th17 cells to psoriasis development." (PMID 41301460, 2025). "Targeting IL-17A and IL-17 receptors using antibodies (e.g., the IL-17 inhibitor secukinumab and the IL-17R inhibitor brodalumab) has achieved remarkable success in treating psoriasis." (PMID 40821838, 2025). "For example, patients with psoriasis and comorbid depression have shown elevated serum concentrations of IL-6, IL-18, and IL-17A." (PMID 40077004, 2025). "To further elucidate the role of LINC01206 in psoriasis, we examined its expression in psoriatic lesions and IL‐17A‐stimulated NHEK cells." (PMID 40670887, 2025). "Psoriasis is classified as a T cell-mediated disorder, as T cell-derived cytokines like IL-17A and IL-22 are responsible for the hyperproliferation and abnormal differentiation of keratinocytes, leading to the formation of psoriatic plaques." (PMID 39859462, 2025). "In humans, treatments for psoriasis that inhibit IL-17A have also been observed to alleviate psychological symptoms in individuals with ASD." (PMID 40497203, 2025). "These compounds aim to suppress Th17 differentiation and inhibit the production of pro-inflammatory cytokines like IL-17A and IL-17F, which are significant contributors to skin inflammation and keratinocyte hyperproliferation in conditions like psoriasis." (PMID 41301460, 2025). "Compared to IL-17A, IL-17F, and IL-17A/F heterodimers, IL-17B, IL 17C, IL-17D, and IL-17E are less characterized in the context of psoriasis." (PMID 40243580, 2025). "Overall, the findings suggest that selected phytochemicals from E. neriifolia exhibit promising interactions with IL‐17A, supporting their possible therapeutic role in psoriasis." (PMID 41416116, 2025). "In psoriasis, Th17 cells produce IL-17A and IL-22, cytokines that lead to keratinocyte proliferation and contribute to the thick, scaly plaques characteristic of the disease​." (PMID 40161116, 2025). "Vunakizumab (SHR-1314), a subcutaneously administered anti-IL-17A IgG1/κ antibody used in the treatment of psoriasis and ankylosing spondylitis, entered a TED trial but was discontinued early for commercial reasons." (PMID 40807149, 2025).